GOLM1 (golgi membrane protein 1)
Diseases named in the same sentence as GOLM1 in open-access papers (continued):
Sharing a sentence is not in itself a finding about the gene and the disease.
ovarian carcinoma (1 paper, 2022). A malignant neoplasm originating from the surface ovarian epithelium. "GOLM1 acts as an initial oncogenic driving gene by promoting ovarian cancer invasion and metastasis through modulating B7-H3 protein maturation and secretion." (PMID 35116068, 2022). "Collectively, we proved that GOLM1 regulates ovarian cancer progression and metastasis though enhancing soluble B7-H3 level." (PMID 35116068, 2022). "Both of these evidences suggest that GOLM1 was important for ovarian cancer development through regulating B7-H3 protein distribution, which provide further insight towards the B7-H3 targeting therapy and mechanism for ovarian cancer." (PMID 35116068, 2022). "This study was aimed at exploring whether the Golgi membrane protein 1 (GOLM1) enhanced ovarian cancer metastasis through B7-H3-dependent way." (PMID 35116068, 2022). "Importantly, GOLM1 acts as a vital oncogene by promoting ovarian cancer metastasis through modulating B7-H3 protein maturation and secretion." (PMID 35116068, 2022). "However, GOLM1 expression pattern in ovarian cancer was not well studied yet." (PMID 35116068, 2022).
tumor (102 papers, 2008 to 2026). "Although GOLM1 has been recognized as an oncogene that promotes several malignancies, a recent study provides evidence that this protein acts as a tumor suppressor in colitis-associated colorectal cancer." (PMID 35805075, 2022). "GOLM1 is expressed at low levels in normal cells but is significantly upregulated in various cancers (e.g., liver, lung, prostate), with its expression level closely linked to tumor aggressiveness and poor prognosis." (PMID 39992528, 2025). "Notably, GOLM1 expression was found to be positively associated with the proportions of tumor-infiltrated immunocytes." (PMID 36468024, 2022). "GOLM1 is involved in promoting tumour immune evasion and metastasis by attracting myeloid‐derived suppressor cells." (PMID 41031610, 2025). "Golgi protein 73 (GP73), a Golgi apparatus-associated protein encoded by GOLM1, is up-regulated in both tumor tissues and serum of HCC patients, functioning as a diagnostic biomarker." (PMID 39022745, 2024). "Our TGCA data analysis has revealed potential relevance of B4GT1 and GOLM1 in tumorigenesis and tumor progression." (PMID 38608280, 2024). "Survival plots revealed a significant decrease in overall survival (OS) and disease-free survival (DFS) among tumor samples exhibiting elevated GOLM1 or B4GALT1 expression (n = 89) compared with those with low expression (n = 89)." (PMID 38608280, 2024). "GOLM1 has been identified as a potential target for cancer therapy, because it is overexpressed in many solid tumors, promotes tumor growth and metastasis, and leads to poor survival." (PMID 39190284, 2024). "Among the 16 novel associated proteins, analysis of TGCA data also revealed potential relevance of B4GT1 and GOLM1 with tumor development." (PMID 38608280, 2024). "In cancer cells, GOLM1 has the ability to be released into the cytoplasm and acts as a molecular chaperone to interact with various tumour‐related molecules such as EGFR, RTK, MMP2, MMP7 and B3‐H7, exerting a pro cancer effect." (PMID 39470578, 2024). "GOLM1, known as GP73 or GOLPH2 and overexpressed in multicancer including PCa, plays a crucial role in the tumor immune microenvironment." (PMID 37122696, 2023). "The GOLM1 protein was localized in the cytoplasm of tumor cells, with higher levels in poorly differentiated HNSCC tissues." (PMID 36499755, 2022). "Higher expression of GOLM1 in tumor tissues than in normal tissues was observed in most tumor types (p < 0.05, 85.19%, 23/27)." (PMID 36468024, 2022). "HNSCC tumor cores from TMAs were selected as cases and divided into four groups according to the expression of GOLM1 and FAM49B." (PMID 36499755, 2022). "We demonstrated that GOLM1 was the key regulator of B7-H3 protein formation and secretion; reduced GOLM1 levels dampened B7-H3 secretion, which is initial for tumor metastasis and invasion both in vitro and in vivo." (PMID 35116068, 2022). "GOLM1 also regulates tumor microenvironment by suppressing CD8+ T cells and activating endoplasmic reticulum stress in tumor-associated macrophages." (PMID 35948172, 2022). "Other studies reported that GOLM1 promotes tumor metastasis by participating in the epithelial-mesenchymal transformation and recycling of epidermal growth factor receptor and receptor tyrosine kinases." (PMID 36211823, 2022). "Several studies have indicated that GOLM1 plays a crucial role in promoting tumor cell invasion, migration, growth, and metastasis in liver and prostate cancers." (PMID 33649292, 2021). "In recent years, the possible effects of GOLM1 involved in the potential regulation of tumor progression attracted growing attention." (PMID 33414427, 2021). "First, we evaluated the immunophenotypes of tumor-infiltrating immune and PD-L1 expression profile in HCC with various GOLM1 levels and found that the overexpression of GOLM1 is associated with TAM infiltration and decreased NK cells in HCC tissues." (PMID 34795203, 2021).
tumor (continued). "The expression of GOLM1 in patient 1, patient 2, patient 7 and patient 8 significantly increased in tumor samples compared with adjacent samples (P < 0.01)." (PMID 33649292, 2021). "Tumors from MUP-uPA mice fed the HFHC diet exhibited an increased expression of tumor markers Ly6d, Cd44, Golm1, and Birc5, as well as higher levels of the proliferation marker Mki67." (PMID 34439245, 2021). "In this study, we found that GOLM1 was overexpression in CRC and the elevated GOLM1 correlated with a higher recurrence rate, shorter overall survival and more aggressive tumor phenotype." (PMID 34729117, 2021). "Further research is needed to reveal the oncogenic functions of GOLM1 that are regulated by the tumor-suppressive miR-143/145 cluster or by miR-27b in PCa." (PMID 25115396, 2014). "Therefore, GOLM1 has a diverse role in various malignancies, including maintenance of inflammation, tumor initiation and metastasis, as well as early diagnosis." (PMID 38997719, 2024). "Furthermore, the GOLM1 gene, encoding a resident cis-Golgi membrane protein, promote epithelial–mesenchymal transition (EMT) and tumor cell proliferation, activating matrix metalloproteinase-13 (MMP13) signaling events that contribute to NSCLC aggressiveness." (PMID 39766023, 2024). "Previous studies and pan cancer analysis of TCGA data both have indicated that GOLM1 is upregulated in multiple tumours, suggesting that GOLM1 may be a key regulator for malignant progression." (PMID 39470578, 2024). "GOLM1 induces tumor growth and metastasis and leads to poor survival in patients." (PMID 35805075, 2022). "Similarly, immunohistochemistry analysis showed a higher expression of GOLM1 in tumor than in adjacent tissue." (PMID 36211823, 2022). "In addition, GOLM1 knockdown significantly reduced tumor formation and metastasis in immunodeficient mice, which is similar with B7-H3 knockdown group." (PMID 35116068, 2022). "Our study found that compared with normal tissues, the expression of GOLM1 was increased in tumor tissues, and the degree of increase may be correlated with the differentiation degree of the tumor." (PMID 36499755, 2022). "In addition, qPCR assays also validated that GOLM1 was upregulated in HCC tumor samples of 127 patients." (PMID 33414427, 2021). "Finally, we focused on the GOLM1 gene because this gene has been identified as a putative target of tumor-suppressive miR-27b and because miR-27b is a predictor of time to CRPC." (PMID 25115396, 2014). "Furthermore, our recent study demonstrated that the tumor-suppressive miR-143/145 cluster commonly targets GOLM1 and that silencing of GOLM1 significantly inhibits the migration and invasion of PCa cells." (PMID 25115396, 2014). "Key bacterial taxa identified in our study, including Methyloversatilis discipulorum, may contribute to immune evasion and tumour progression by upregulating GOLM1, recruiting MDSCs, and enhancing PD‐L1 stability and transport, ultimately inhibiting CD8+ T cell function." (PMID 41031610, 2025). "Therefore, GOLM1 has the potential to become a new tumor biomarker." (PMID 33649292, 2021). "Furthermore, GOLM1-KD significantly decreased the PD-L1 expression on both tumor cells and TAMs." (PMID 34795203, 2021). "Interestingly, 68% of tumor tissues showed co-expression of Golm-1 and CDH2." (PMID 28486946, 2017). "Overall, GOLM1 recruitment of Rab11 and EGFR/RTK led to EGFR-mediated signalling and tumour migration." (PMID 40293576, 2025). "The boxplot analysis revealed a statistically significant increase in GOLM1 and B4GALT1 expression in the tumor samples as compared with the normal control group." (PMID 38608280, 2024). "Gp73−/− mice were then mated with HBV; Pten−/− mice to illustrate the role of hepatic tumor biomarker golgi membrane protein 73 (GP73)/ golgi membrane protein 1 (GOLM1) in hepatic oncogenesis." (PMID 38459588, 2024). "In comparison to normal tissues, tumor tissues have significantly increased levels of COL1A1 and GOLM1 protein expression." (PMID 38001428, 2023).
tumor (continued). "In contrast, the expressions of GOLM1 and RTKN in the tumor tissues (8.549 ± 1.034 and 1.782 ± 0.228, respectively) were significantly higher than those in the adjacent normal tissues (1.766 ± 0.113 and 1.247 ± 0.128, respectively) (p < 0.001 and p = 0.018)." (PMID 37373169, 2023). "GOLM1 was overexpressed in HCC tissues compared with controls, and its level correlated with tumor purity and prognosis." (PMID 36211823, 2022). "Further research is essential to reveal the function of GOLM1 and FAM49B in HNSCC cells, explore the interaction among GOLM1, FAM49B, and other genes, and build mouse tumor-bearing models to find potential drugs for HNSCC treatment." (PMID 36499755, 2022). "The correlation between the expression of GOLM1 and FAM49B in tumor cells and clinicopathological characteristics was first studied." (PMID 36499755, 2022). "We indicated that the high expression of both FAM49B and GOLM1 in HNSCC tissues predicted a worse prognosis, possibly as a result of the regulation of immune infiltrating cells in the tumor environment." (PMID 36499755, 2022). "First, we profiled the differentially expressed genes in HCC using TCGA data by “UALCAN” algorithm, and found that, GOLM1, a previously reported oncogene, was highly expressed in HCC tumor samples and upregulated in most cancer types." (PMID 33414427, 2021). "GOLM1, also known as GOLPH2 and GP73, is a type II transmembrane protein of the Golgi cisternae, which is highly expressed in tumor cells and is regarded as a potential cancer cell marker." (PMID 32850310, 2020). "Through RT-qPCR and IHC, we found that the expression levels of GOLM1 messenger RNA (mRNA) and protein in LSCC tumor tissues were significantly higher than those in matched non-tumor tissues." (PMID 32850310, 2020). "Validation of selected mRNAs was performed on the same patients cohort by RT-qPCR and, according to the expression profiling results, we evidenced the up-regulation of Golm-1, Psat-1 and CDH2 in tumor tissues compared to normal samples." (PMID 28486946, 2017). "Inhibition of Notch abnormal expression by drugs can inhibit the tumor progression of intestinal epithelial cells lacking Golgi membrane protein-1, suggesting that Golgi membrane protein-1 prevents colon tumorigenesis by regulating Notch signaling pathway." (PMID 39691600, 2024). "Furthermore, studies suggest that receptor tyrosine kinases (RTKs) play a critical role in malignant tumor transformation and cancer metastasis and that cholesterol inhibits RTK autophagic degradation in a GOLM1-dependent manner." (PMID 38376693, 2024). "In addition, we conducted an immunohistochemistry analysis to identify the expression of GOLM1 and FAM49B in the tumor samples." (PMID 36499755, 2022). "While untreated Golm1−/− mice exhibited no morphological abnormality, the treated Golm1−/− mice displayed an increased colon tumor burden and an enhanced colon to body weight ratio compared to WT mice." (PMID 33850109, 2021). "Taken together, these findings suggested that the overexpression of GOLM1 may contribute to the immunosuppressive microenvironment in HCC and immune-escape of tumor cells." (PMID 34795203, 2021). "The results revealed that hypoxia stimulated cells to synthesize EVs proteins involved in enhancing tumour cell proliferation (NRSN2, WISP2, SPRX1, LCK), metastasis (GOLM1, STC1, MGAT5B), stemness (STC1, TMEM59), angiogenesis (ANGPTL4), and suppressing host immunity (CD70)." (PMID 33050615, 2020). "Several of these HSEPs have been reported in other contexts to play key roles in tumour progression by cancer cell proliferation (NRSN2, WISP2, SPRX1, LCK), metastasis (GOLM1, STC1, MGAT5B), and stemness (STC1, TMEM59), as well as promoting angiogenesis (ANGPTL4) and host immunosuppression (CD70)." (PMID 33050615, 2020).
tumor (continued). "Considering the fact that c-Myc is an important transcription factor in tumor progression and c-Myc positively regulates GP73 expression, it could be hypothesized that c-Myc targets the promoter of GOLM1 and activates its transcription." (PMID 31591387, 2019). "Of note, GOLM1, another protein of the Golgi apparatus that is overexpressed in some types of tumor cells, regulates EGFR recycling without affecting its glycosylation, suggesting that GOLPH3 could also directly affect EGFR recycling." (PMID 33238647, 2020). "However, the connection between GOLM1 and UVM, particularly its role in regulating inflammatory/immune responses in this tumor, has not been investigated." (PMID 36468024, 2022).
cancer (71 papers, 2008 to 2025). A tumor composed of atypical neoplastic, often pleomorphic cells that invade other tissues. "While GOLM1 was reported as a promising diagnostic cancer marker, its biological function is unclear." (PMID 24243830, 2013). "Furthermore, GOLM1 acted as an oncogene linked with poor prognosis in the combined meta-analysis of 32 types of cancer (p < 0.001, HR: 2.11, 95% CI: 1.30–3.43)." (PMID 36468024, 2022). "We performed GSEA and found that the expression of GOLM1 was mainly associated with malignancies, including “adherents junction”, “cell cycle”, “pathway in cancer”, which inferred that GOLM1 may play an important role in the course of malignant tumors." (PMID 33649292, 2021). "Golgi membrane protein 1 (GOLM1) was implicated in carcinogenesis of multiple types of cancer." (PMID 33649292, 2021). "According to our research, PSMD1 plays a pivotal role as a target molecule for GOLM1 in facilitating a pro‐cancer function in PCa." (PMID 39470578, 2024). "GOLM1 is a glycosylated protein that is present on the cis-Golgi cisternae and highly expressed in various cancers, including NSCLC." (PMID 37373169, 2023). "In recent years, GOLM1 has been identified as a multifunctional protein that promotes cancer progression and epithelial–mesenchymal transition in cancer cells." (PMID 37373169, 2023). "Transcripts of AMACR, GOLM1, TRPM8 and NKX3-1 genes were overexpressed and were closely associated with cancer aggressiveness, extracapsular extension and vesicular seminal invasion." (PMID 37091783, 2023). "GOLM1/GP73 is known to be involved in the pathogenesis of many cancers, and its expression is elevated in hepatocytes also under other disease conditions." (PMID 35948172, 2022). "Given the importance of GOLM1 in cancers, its prognostic value, functional role, and potential mechanisms in UVM have aroused wide research interest." (PMID 36468024, 2022). "Many studies have suggested that GOLM1 can function as a promoter of oncogenic phonotype in several cancer types." (PMID 33869063, 2021). "Golgi membrane protein 1 (GOLM1), a transmembrane glycoprotein of the Golgi cisternae, is involved in the carcinogenesis of many types of cancers." (PMID 34540835, 2021). "More and more evidence has indicated that the deregulation of GOLM1 plays a crucial role in cancer progression." (PMID 34729117, 2021). "With the rise of researches about micro-RNA (miRNA) in recent years, some studies manifest that the levels of multiple miRNAs targeting the 3′-untranslated region (3′-UTR) of GOLM1 are attenuated in cancer cells, but the regulatory mechanism is still unclear." (PMID 34950590, 2021). "Accumulating evidence has indicated that the deregulation of GOLM1 gene plays critical roles in cancer progression 10, 11, metastasis 12 and immunosuppression." (PMID 34729117, 2021). "GOLM-1 protein expression has been reported to be highly upregulated in cancer tissues and high GOLM-1 expression has been related to poor outcome." (PMID 30622242, 2019). "Additionally, our previous findings demonstrate that GOLM1 plays a pro‐cancer role in PCa by activating the PI3K‐Akt signal." (PMID 39470578, 2024). "In addition, the critical implication of GOLM1 in the prevention, prediction, and treatment of cancer has been established." (PMID 36468024, 2022). "In addition, high levels of soluble GOLM1 are detected in the serum of several cancers, while B7-H3 protein has also been found in the secretome, including exosomes and other extracellular vesicles." (PMID 35116068, 2022). "Furthermore, changes relating to “adhesion” and binding”, which are more enriched in GOLM1 overexpression, correlated highly with cancer cell invasion and migration." (PMID 33649292, 2021). "Nowadays, little is known about biological functions and molecular mechanisms of GOLM1 in cancer." (PMID 33649292, 2021).